INS (insulin)
Diseases named in the same sentence as INS in open-access papers (continued):
Sharing a sentence is not in itself a finding about the gene and the disease.
Insulin resistance (continued). "Indeed, peripherally synthesized ceramides, released into the bloodstream under conditions of obesity or T2D, can transit across the BBB, alter insulin signaling and induce insulin resistance in the brain." (PMID 36671568, 2023). "However, the function of FGF21 is affected to varying degrees when insulin resistance or insulin signal transduction disorder occurs." (PMID 38069273, 2023). "However, excess systemic insulin can lead to insulin resistance, which results in diminished cellular response." (PMID 37934726, 2023). "By constructing the PCOS model, we found that CRP knockout rats showed better glucose disposal ability and higher insulin sensitivity than wild-type rats in GTT and ITT tests, which further reflected that CRP may be implicated in insulin resistance in PCOS." (PMID 37660067, 2023). "Likewise, patients with higher LR Score values had lower insulin sensitivity (P = 0.006) and higher liver insulin resistance (P = 0.005)." (PMID 37537576, 2023). "In individuals with excessive body fat mass, lipocalin-2 is an inflammatory marker produced by adipocytes and being so as a mediator for chronic low-grade inflammation, which subsequently disturbs insulin signaling and contributes to the development of insulin resistance and type 2 diabetes." (PMID 37238398, 2023). "Whereas acute insulin treatment may benefit ApoE ε4 non-carriers with normal insulin levels, chronic treatment may, in fact, induce insulin resistance perhaps explaining a decline in memory function in response to insulin detemir." (PMID 36258018, 2023). "Elevated systolic blood pressure or hypertension has also been shown to be an outcome of insulin resistance, as insulin has been shown to exert a peripheral vasodilatory effect by stimulating the production of endothelial nitric oxide and improving arterial stiffness." (PMID 37960272, 2023). "Another contributing factor is insulin resistance and impaired insulin signaling in the brain." (PMID 37610708, 2023). "During T2DM progression, obesity and insulin resistance increase insulin secretion to trigger a vicious cycle of hyperinsulinemia and insulin resistance that ultimately results in β-cell failure via β-cell degranulation, trans/dedifferentiation, and, to some extent, apoptosis." (PMID 37188647, 2023). "The addition of the PTP1B inhibitor almost completely counteracted the reduction in insulin-stimulated IR and AKT phosphorylation after HCI following NFD or HFD, suggesting that PTP1B activation plays a causal role in HFD- and HCI-induced insulin resistance in plantaris muscle." (PMID 37389126, 2023). "We conclude that rapid muscle insulin resistance observed with 2 days of forearm immobilisation is accompanied by early signs of reduced net muscle amino acid balance in both fasting and insulin-stimulated conditions, which is accompanied by an increase in amino acid efflux from muscle." (PMID 37873346, 2023). "In addition, in obesity, inflammatory reactions implicate reduced insulin sensitivity of hypothalamic neurons and favor the development of insulin resistance at both central and peripheral levels." (PMID 37298571, 2023). "Hyperinsulinemia can maintain normal blood glucose levels to some degree; however, chronic progressive insulin resistance and compensatory insulin hypersecretion can be beta cell stress and eventually to beta-cell failure, leading to prediabetes and then to type 2 diabetes." (PMID 36909337, 2023). "Moreover, Rnf13HKO mice manifested worse glucose tolerance, as indicated by the glucose tolerance test (GTT), and impaired insulin resistance, as indicated by the insulin tolerance test (ITT)." (PMID 37857628, 2023). "Insulin resistance sensitizes the vascular smooth muscle cells through high levels of insulin, interferes with the control of blood pressure by the renin-angiotensin-aldosterone system, increases the resistance of vascular smooth muscle, and leads to hypertension and myocardial remodeling." (PMID 37900136, 2023).
Insulin resistance (continued). "A randomized control trial revealed that the ChE inhibitor galantamine could lower the level of TNF, a molecule that contributed to insulin resistance, and also significantly lower plasma insulin and HOMA-IR in patients with metabolic syndrome." (PMID 37138337, 2023). "Thirdly, hyperglycemia-induced insulin secretion may lead to peripheral or cerebral insulin resistance, which is related to neurodegeneration, neuronal vulnerability, and other pathological lesions." (PMID 37533764, 2023). "The high-fat and high-sugar diet used in this study was improved according to the previous relevant literature, and the improved diet could fully induce abnormal insulin secretion of target organs and gradually result in insulin resistance." (PMID 37830511, 2023). "Preptin levels are affected by fasting insulin and insulin resistance." (PMID 37434133, 2023). "Insulin resistance may be related to the development of multiple complications in different insulin-sensitive tissues." (PMID 38132872, 2023). "Here the authors show that glucocorticoid receptor-deficient macrophages have an elevated inflammatory response which aggravates insulin resistance implicating that glucocorticoids promote insulin-sensitizing actions via adipose tissue macrophages during obesity." (PMID 37080971, 2023). "Insulin resistance is characterised by reduced cell-surface GLUT4 in response to insulin." (PMID 37248992, 2023). "Abnormal fluctuations in intracellular calcium levels in insulin target organs may contribute to peripheral insulin resistance, through impaired insulin signal transduction and glucose transporter function." (PMID 37495647, 2023). "Consequently, reduced glucose uptake, vasodilation, and insulin secretion are experienced, resulting in the progression of insulin resistance." (PMID 37106780, 2023). "Insulin resistance stems from the inability of insulin to transport glucose to tissues which may exert an influence on body composition." (PMID 36915133, 2023). "Therefore, through in-depth research, we explored the effects of AH extracts on glycemia, insulin levels, and insulin resistance in animal models and prediabetic subjects supplemented with AH for 12 weeks." (PMID 37895834, 2023). "HSD17B6, hydroxysteroid 17-beta dehydrogenase 6, is involved in androgen catabolism and has been implicated in polycystic ovarian syndrome (PCOS), including metabolic perturbations correlated with PCOS, including increased BMI, fasting insulin, and insulin resistance." (PMID 37345113, 2023). "It is known that many steps of the insulin signaling pathway may be disturbed, leading to insulin resistance." (PMID 38203600, 2023). "Several mechanisms have been proposed to explain how ceramides might induce insulin resistance, including: 1) ceramides impair insulin activation of AKT through two mechanisms: impaired AKT translocation via activation of PKCζ or activation of PP2A." (PMID 36594091, 2023). "This combined treatment for 10 min, twice weekly, could lower insulin resistance, insulin levels, and fasting blood glucose." (PMID 36768170, 2023). "In addition to medications lowering insulin demand and enhancing insulin responsiveness, nutritional interventions, including calorie restriction, are also important in the treatment of insulin resistance." (PMID 36838411, 2023). "Moreover, insulin resistance is a physiological state in which insulin-targeting tissues exhibit reduced responsiveness to high physiological levels of insulin." (PMID 37240157, 2023). "Insulin-resistant human and rodent muscle exhibit impaired insulin-stimulated GLUT4 translocation and muscle-specific deletion of GLUT4 is sufficient to cause systemic insulin resistance and glucose intolerance." (PMID 37073948, 2023). "In rodent models of insulin resistance, blood insulin levels may be increased (hyperinsulinemia) or decreased (hypoinsulinemia), depending on the experimental model." (PMID 38203600, 2023).
Insulin resistance (continued). "Some omentin genetic variations may change insulin metabolism and have key roles in developing type 2 diabetes (T2D) through insulin resistance." (PMID 37568613, 2023). "The proportion of type I myofibers correlates with insulin responsiveness and may be involved in the etiology and insulin resistance in obesity." (PMID 37592340, 2023). "It was later demonstrated that only a distinct IgG glycoform—hyposialylated IgG, is likely responsible for obesity-related genesis of insulin resistance, driven by enhanced activation of endothelial FcγRIIB receptor, which consequently impairs insulin delivery to the skeletal muscle." (PMID 37079606, 2023). "Unfortunately, there is no widely acknowledged treatment or preventative strategy for GDM at the moment, except lifestyle modification (diet and exercise) and, on occasion, insulin therapy, which is only of limited value due to the insulin resistance that is commonly present." (PMID 38021940, 2023). "Previously when stratified according to pathophysiologic subtype of GDM (insulin resistance, beta-cell deficiency, or mixed), total TG was higher and HDL cholesterol lower in the insulin-resistant compared to the beta-cell-deficient subgroup —largely in agreement with our findings." (PMID 36979405, 2023). "Furthermore, in future studies, we plan to conduct a more extensive investigation into the correlation between TH and insulin sensitivity as well as insulin resistance." (PMID 38053730, 2023). "Therefore, in order to better study IR in large-scale epidemiological investigations, researchers have developed some non-insulin-based evaluation indicators that have become predictive factors and biomarkers of insulin resistance." (PMID 38523869, 2023). "In all cases, hyperglycemia was accompanied by an increase in insulin concentration, which indirectly suggests the presence of insulin resistance, although confirmation of this phenomenon would require additional tests (for example, an oral glucose tolerance test)." (PMID 37259305, 2023). "Excessive visceral fat also creates insulin resistance and increases the insulin level." (PMID 37700299, 2023). "The values of the plasma sestrin 2, TRB3, insulin, fasting plasma glucose, lipid profile, and homeostasis model assessment of insulin resistance (HOMA-IR) were compared in 90 obese women with PCOS (BMI > 30), 90 women with nonobese PCOS (BMI < 30), and 90 control patients (BMI < 30)." (PMID 38813505, 2023). "Results reported here suggest that insulin signalling may be disrupted in AD brains by mechanisms similar to those leading to insulin resistance in T2DM patients who received pioglitazone treatment." (PMID 37095270, 2023). "In PCOS-afflicted women, cinnamon dramatically decreased fasting insulin and insulin resistance." (PMID 37383339, 2023). "The elevated glucose levels, impaired insulin secretion and insulin resistance interconnected with the development of advanced glycation end products (AGEs) are characteristics of type 2 diabetes and are a contributing determinant of the pathogenesis of cardiovascular diseases (CDs)." (PMID 36769283, 2023). "Lip-BBR could be useful in T2DM via promoting insulin secretion, reduction of insulin resistance, gluconeogenesis, glucose uptake activation and glycolysis, and reducing inflammation." (PMID 37371950, 2023). "Physiologically, lack of physical activity may be tied to decreased glucose uptake and subsequent elevated blood glucose and insulin action dysfunction, both of which contribute to insulin resistance." (PMID 37265574, 2023). "T2DM is characterized by insulin resistance that leads to insulin ineffectiveness." (PMID 36677012, 2023). "Thus, when obesity is present and insulin resistance is established, the pancreas secretes more insulin and excess insulin results in increased fat storage in the adipocytes." (PMID 37513524, 2023). "It impairs the body's ability to utilize insulin, leading to insulin resistance effectively." (PMID 37719547, 2023).
Insulin resistance (continued). "However, during insulin resistance (IR), when insulin signalling is blunted and accompanied by hyperinsulinaemia, the promotion of hepatic DNL continues unabated and hepatic steatosis increases." (PMID 37735236, 2023). "As well as associations with indexes of insulin resistance, fasting and OGTT 120 min GLP-1 concentrations were both positively associated with the index of insulin secretion used (the ratio of areas under the insulin and glucose concentrations, 0–120 min)." (PMID 37439859, 2023). "Furthermore, inhibiting CCL4 with a specific antibody has been found to attenuate systemic inflammation, improve insulin resistance, and reduce circulating insulin levels in both type 2 diabetes animal models and metabolic syndrome animal models." (PMID 37287987, 2023). "An increased glucagon/insulin ratio is another marker of insulin resistance." (PMID 37509329, 2023). "Because insulin and C-peptide assays are difficult to perform, a basic indicator that identifies insulin resistance could benefit clinical hypertension management." (PMID 37759253, 2023). "Insulin resistance induced by MetS might promote carcinogenesis through insulin, insulin-like growth factor 1 signaling, and systemic inflammation." (PMID 37324025, 2023). "It is thought that insulin resistance and high insulin levels may contribute to the up-regulation of betatrophin levels." (PMID 37434133, 2023). "The reduction in LDL, cholesterol, and triglyceride could be a key contributor to reducing insulin resistance which might explain the improvement of insulin sensitivity observed in our study." (PMID 36677559, 2023). "Here, the authors show, using global phosphoproteomics, that insulin resistance is caused by a marked rewiring of both canonical and non-canonical insulin signalling, and includes dysregulated GSK3 activity." (PMID 36808134, 2023). "In patients with polycystic ovary syndrome, increased ET-1 levels are thought to contribute to the development of insulin resistance, which could be via the inhibition of glucose uptake and insulin-stimulated Akt phosphorylation." (PMID 37511055, 2023). "Insulin resistance impairs glucose metabolism, leading to a compensatory increase in insulin production and hyperinsulinemia and may subsequently lead to metabolic syndrome." (PMID 35986887, 2023). "Interestingly, podocytes are insulin sensitive, and evidence has indicated that long-term exposure of podocytes to high glucose induces insulin resistance and leads to impaired function of podocytes." (PMID 36792603, 2023). "Type two diabetes begins with a lack of insulin action caused by decreased insulin secretion and insulin resistance." (PMID 37375710, 2023). "In addition to this beneficial effect on glycemia, ginger powder has been shown to decrease serum insulin resistance and significantly improve insulin levels and hemoglobin A1c." (PMID 36900554, 2023). "CLM as a novel microbial ingredient elicited substantially positive anti-diabetic effects during the intake period (12 weeks), involving especially ameliorated glycemic control of FBG, peripheral insulin action, and reduced C-peptide and HbA1c, via improving insulin resistance." (PMID 36934269, 2023). "However, as disposition index is calculated via adjustment for insulin resistance, the reduced disposition index cannot a priori exclude the possibility of reduced insulin sensitivity either at hepatic or skeletal muscle level." (PMID 37333553, 2023). "In summary insulin resistance is defined as the inability of certain tissues in the body to receive feedback to normal insulin levels in the body and the need for higher insulin levels to ensure that the body produces a normal response to insulin." (PMID 37089923, 2023). "As the most significant insulin resistance develops in the third trimester, factors leading to increase in insulin synthesis and secretion during early pregnancy might be independent of the decline of insulin sensitivity." (PMID 37079606, 2023).
Insulin resistance (continued). "Again, the homeostatic model of insulin resistance requires glucose and insulin levels in the fasting state that could be challenging to obtain in large trials for multiple visits." (PMID 37960272, 2023). "However, the classical methods used for measurement of insulin resistance (i.e., euglycemic insulin clamp and intravenous glucose tolerance testing) cannot be widely applied in the clinical setting owing to their high cost and invasiveness." (PMID 38057801, 2023). "Chronic hyperglycemia, which induces insulin resistance, was found to reduce the insulin-secreting capacity of pancreatic beta cells by altering metabolic pathways, causing endoplasmic reticulum stress, altering intracellular Ca2+ levels and altering the activity of K+− ATP channels." (PMID 37298274, 2023). "Thus, insulin resistance in obesity is exhibited by reduced insulin-stimulated glucose transport and metabolism in adipocytes, and by impaired suppression of hepatic glucose production." (PMID 36735680, 2023). "As MLE improved insulin resistance in rats, insulin levels decreased." (PMID 37667364, 2023). "Before onset of pre-diabetes or overt DM, mechanisms such as insulin hyper-secretion and reduced renal insulin clearance may effectively compensate for insulin resistance." (PMID 37689695, 2023). "CR reduces insulin resistance and insulin levels, which may reduce the PI3K/AKT signaling and in turn increase the FOXO3A upregulation and transcriptional activity." (PMID 37823711, 2023). "In this study, we found that ATMP could effectively improve glucose tolerance and alleviate insulin resistance by promoting insulin secretion and inhibiting glucagon secretion." (PMID 36845056, 2023). "Given the fact that the anti-natriuretic effect of insulin is intact, this may lead to enhanced kidney salt absorption in individuals with insulin resistance." (PMID 36901725, 2023). "For HOMA-IR, insulin-based values may overestimate insulin resistance among individuals on insulin medication." (PMID 37402743, 2023). "In addition, a functional study in rats in which insulin resistance was induced by high-fat diet, showed that insulin-stimulated glucose uptake into muscle was lower and that this was driven by lower uptake in type II fibres specifically." (PMID 37333553, 2023). "Type 2 diabetes may be due either by insufficient insulin production by the beta cells of the pancreatic islets or by defective action in peripheral tissues (muscle, liver) also called insulin resistance." (PMID 38139339, 2023). "Disrupted insulin responses to food, overfeeding, and overweight/obesity all contribute to the onset and progression of insulin resistance and metabolic syndrome, which eventually may lead to β-cell failure and type-2 diabetes (T2D)." (PMID 37819196, 2023). "Furthermore, insulin as such improves the mitochondrial function, which is prevented by palmitate as a known inducer of insulin resistance." (PMID 37049441, 2023). "Insulin effectively suppresses the production of triglycerides in the liver, and various research conducted on animals have found a potential link between intermittent hypoxia and the development of insulin resistance in lean mice." (PMID 37752495, 2023). "That is, insulin levels may be mildly elevated and peripheral insulin resistance occurs, which more closely resembles T2D than T3cD of other etiologies." (PMID 36672448, 2023). "There are various methods for measuring insulin resistance and insulin secretion dysfunction." (PMID 36788521, 2023). "Similar to the pathogenesis of type 2 diabetes, PTDM may be a result of variable degrees of insulin resistance and impaired insulin secretion by the pancreatic β-cells." (PMID 38068348, 2023). "It arises due to a combination of insulin resistance and inadequate insulin secretion." (PMID 37763235, 2023).